HS3ST4 (heparan sulfate-glucosamine 3-sulfotransferase 4)
Description:
Sulfotransferase that utilizes 3'-phospho-5'-adenylyl sulfate (PAPS) to catalyze the transfer of a sulfo group to the 3-O-position of an N-sulfoglucosamine residue in heparan sulfate. Is able to install the 3-O-sulfo group in a disaccharide domain consisting of -GlcA2S-GlcNS- to form the -GlcA2S-GlcNS3S-sequence, and in -IdoA2S-GlcNS-IdoA2S- to form -IdoA2S-GlcNS3S-IdoA2S-. Does not sulfate the -GlcA-GlcNS-IdoA2S-domain.
Synonyms: 3-OST-4; h3-OST-4; 3OST4; 30ST4
Tractability: Antibody: UniProt predicts a signal peptide or a membrane-spanning region.
Gene: Protein-coding gene on chromosome 16 (25,691,959 to 26,137,685, forward strand). Ensembl gene ENSG00000182601.
Subcellular location: Golgi apparatus membrane
Pathways (Reactome):
Metabolism: HS-GAG biosynthesis
Gene Ontology:
Molecular function: [heparan sulfate]-glucosamine 3-sulfotransferase activity; sulfotransferase activity
Biological process: heparan sulfate proteoglycan metabolic process; heparan sulfate proteoglycan biosynthetic process
Cellular component: Golgi membrane
Genetic constraint (gnomAD): Loss-of-function variants: 17 observed, 22.47 expected, observed/expected ratio (o/e) 0.76, 90% interval 0.52 to 1.13. The synonymous counts are far from expectation, so gnomAD's model fits this gene poorly and the ratio says little. Missense variants: 602 observed, 528.29 expected, observed/expected ratio (o/e) 1.14, 90% interval 1.07 to 1.22. Synonymous variants: 301 observed, 229.31 expected, observed/expected ratio (o/e) 1.31, 90% interval 1.19 to 1.44.
Homologues: Orthologues: chimpanzee HS3ST4 (99% identical), macaque HS3ST4 (98% identical), pig HS3ST4 (96% identical), rat Hs3st4 (89% identical), mouse Hs3st4 (88% identical), guinea pig HS3ST4 (77% identical), zebrafish hs3st4 (62% identical), Drosophila melanogaster sfl (22% identical), Caenorhabditis elegans hst-1 (21% identical). Paralogues in human: HS3ST2 (51% identical), HS3ST3A1 (49% identical), HS3ST3B1 (48% identical), HS3ST6 (43% identical), HS3ST5 (30% identical), NDST1 (27% identical), HS3ST1 (26% identical), NDST4 (26% identical), NDST3 (25% identical), NDST2 (25% identical).
Diseases named in the same sentence as HS3ST4 in open-access papers:
HS3ST4 is named in the same sentence as 11 diseases in open-access papers, as found by Europe PMC text mining. Sharing a sentence is not in itself a finding about the gene and the disease. The quoted sentences say what the papers report.
asthma (1 paper, 2024). "The 15 most significant DEGs included genes known to play a role in wound healing (FN1, CDH11), immune response (VSIG4, HS3ST4), and asthma drug response (PTHHD4, SPTBN1, FKBP5)." (PMID 38806494, 2024).
Ewing sarcoma (1 paper, 2022). A small round cell tumor that lacks morphologic, immunohistochemical, and electron microscopic evidence of neuroectodermal differentiation. "Specifically, we found upregulation of enzymes involved in the catabolism of heparan sulfate proteoglycans (including SGSH, GNS, HS3ST4, HS3ST1, HS2ST1, and HS6ST1) in human Ewing sarcoma." (PMID 35285802, 2022).
HCMV infection (1 paper, 2021). "At high (5.0) as well as low (0.01) multiplicity of infection (MOI), MCMV growth was significantly reduced in the single Hs3st1 and Hs3st4 knockouts as well as in the double Hs3st1/4 knockouts, indicating that 3-O-sulfation of HS is important for HCMV infection." (PMID 34352038, 2021).
metastatic tumors (1 paper, 2013). "Although some variations were detectable only in non metastatic tumors, most were identified in both IDCs although several genes showed more intense changes in metastatic tumors than in non-metastatic, including PRCAN, CSGALNACT2, HS3ST4 and CHST12." (PMID 23327652, 2013).
cancer (7 papers, 2018 to 2025). A tumor composed of atypical neoplastic, often pleomorphic cells that invade other tissues. "HS3ST4, a member of the heparan sulfate (HS)-modifying enzyme family, has been implicated in cancer progression and immune evasion." (PMID 40128298, 2025). "Silencing of heparan sulfate-glucosamine 3-O-sulfotransferase 4 (HS3ST4) in cancer cells recruits more activated NK cells in the TME." (PMID 36750830, 2023). "Silencing of HS3ST4 expression using short hairpin RNAs in cancer cells resulted in increased tumor infiltration of activated NK cells." (PMID 31134055, 2019). "Pathological expression of HS3ST4 plays a deleterious role in the escape of cancer cells from the immune system." (PMID 30360368, 2018). "On another hand, HS3ST4 was found to be up-regulated in certain cancer cells by increased levels of TRF2, a key factor in telomere protection, which correlated with inhibition of the recruitment of NK cells to the tumor." (PMID 29547633, 2018). "Interestingly, some peaks correspond to TRF2‐bound ITSs (interstitial telomeric sequences) previously characterized in cancer cell lines, such as a binding site at the intron of the HS3ST4 gene, whose expression is regulated by TRF2." (PMID 31991048, 2020). "Accordingly, upregulation of the expression of certain HS3STs, such as HS3ST3B or HS3ST4, may be a mechanism that permits cancer cells to impact NK cell activation and to escape their elimination." (PMID 31249810, 2019). "The same effects were observed with cancer cells carrying an exogenous expression of HS3ST4, suggesting that the isozyme may be involved in a mechanism of immune escape." (PMID 31249810, 2019). "However, the situation is not so clear, and there is accumulating evidence that HS3ST2, HS3ST3A, HS3ST3B, and HS3ST4 may also act as tumor-promoting enzymes in a number of cancer cells depending on their phenotypes and molecular signatures." (PMID 31249810, 2019). "We also showed that HS3ST3B and HS3ST4 shared with HS3ST2 the same promoting effects, which revealed that the expression of these isozymes had similar functional impact on cancer cell behavior." (PMID 30360368, 2018).
tumor (6 papers, 2018 to 2025). "The top interaction involved a SNP in the HS3ST4 gene, which encodes the enzyme heparan sulfate D-glucosaminyl 3-O-sulfotransferase 4 and has been linked to herpes simplex virus type 1 pathogenesis and tumor growth." (PMID 33302579, 2020). "By binding ITSs, TRF2 modulates the HS3ST4 gene, encoding heparan sulfate (glucosamine) 3-O-sulphotransferase 4, which is involved in regulating NK cell recruitment/activation at the tumor site with an impact on tumor take/growth." (PMID 30654820, 2019). "Analysis of GSE99671 revealed significantly higher expression levels of KLK2, NRXN1, HES5, OR2W3, and HS3ST4 in normal samples compared to tumor samples." (PMID 40128298, 2025). "Its upregulation promotes HS3ST4 expression, accelerating tumor growth in vivo and potentially contributing to immune evasion by inhibiting NK cell activation." (PMID 40128298, 2025). "Moreover, exogenous expression of either TRF2 or HS3ST4 in various tumor cell lines similarly resulted in increased tumor growth in xenografted mice, which suggests that the expression of this enzyme may be part of a pro-oncogenic pathway." (PMID 31249810, 2019).
HS3ST4 also shares sentences with these, for which no sentence is quoted: glioblastoma (1 paper); hepatocellular carcinoma (1); infection (1); invasive breast ductal carcinomas (1); pancreatic cancers (1).